ALB (albumin)
Diseases named in the same sentence as ALB in open-access papers (continued):
Sharing a sentence is not in itself a finding about the gene and the disease.
infection (1,185 papers, 2005 to 2026). The state of being infected such as from the introduction of a foreign agent such as serum, vaccine, antigenic substance or organism. "Numerous studies have demonstrated that lower serum albumin levels are strongly associated with increased hospitalization, cardiovascular morbidity, infection-related complications, and all-cause mortality in the hemodialysis population." (PMID 41517580, 2026). "Previous studies have likewise shown that low lymphocyte and albumin levels, along with high platelet counts, are associated with adverse outcomes such as infection, bleeding, vascular complications, and prolonged hospitalization." (PMID 41594252, 2026). "While our study did not examine these complications directly, previous studies have associated low serum albumin to an increase in hospital-acquired infections and a predictor of a prolonged hospital stay." (PMID 40275223, 2025). "Plasma ALB is influenced by various factors (such as infection, blood loss, severe hepatic or renal dysfunction, etc.), and its ability to assess nutritional risk is controversial." (PMID 40880745, 2025). "Significantly more patients in the albumin group had abdominal infectious sources, which are associated with a higher inflammatory response compared to other categorized sources of infection." (PMID 40386509, 2025). "Regular and frequent albumin infusions often necessitate the placement of a central catheter, which is associated with inherent risks such as infection, bleeding, thrombosis, and the need for anticoagulant therapy." (PMID 40266336, 2025). "Conversely, a reduction in serum albumin also indicates a decline in immune function, rendering the body less resistant to pathogens and more susceptible to infections." (PMID 40313464, 2025). "In conclusion, nephrectomy is associated with a decrease in the number of albumin infusions required, infections, and hospitalizations, making it a potential treatment option for selected patients with CNS secondary to the NPHS1 mutation." (PMID 40266336, 2025). "The results indicate that age, duration of surgery, blood transfusion, internal fixation, postoperative NLR and postoperative CRP/ALB are risk factors for the development of infection after spinal surgery." (PMID 41019129, 2025). "Albumin, one of the two main components of serum proteins, is an important marker associated with inflammation and infection." (PMID 40510348, 2025). "The albumin layer serves as a barrier, reducing the adhesion of S. aureus and thereby lowering the risk of infection." (PMID 40565919, 2025). "When serum albumin is <35g/L, the wound-healing ability decreases, and the risk of infection increases." (PMID 41220716, 2025). "Our study observed that lower preoperative albumin levels correlated with increased susceptibility to infection, likely due to the close relationship between albumin levels and nutritional status." (PMID 39773012, 2025). "Some studies have shown that a decrease in albumin concentration can inhibit macrophage activation, impair the immune response, and make patients more susceptible to infection or inflammation after surgery." (PMID 40225039, 2025). "Beyond infection control, curcumin supplementation was associated with improvements in nutritional parameters, including serum albumin, hemoglobin levels, and body mass index." (PMID 41019987, 2025). "Preoperative biomarker trends were also explored, with some studies identifying CRP, albumin, and eGFR as potential predictors of surgical site infection risk in elective procedures." (PMID 40342430, 2025). "Albumin levels are closely related to the risk of postoperative infection, and maintaining serum albumin levels above 30 g/L during the perioperative period of LT can reduce the incidence of postoperative infections." (PMID 40281777, 2025).
infection (continued). "When combined with bone substitute materials, albumin enhances their osteoinductive capacity, reduces resorption, lowers the risk of infection due to its antimicrobial properties, and accelerates the healing process." (PMID 40565919, 2025). "Given the limited sample size and the established role of other key factors, such as biopsy site, BMI, and serum albumin, in infection risk, we decided to retain only these core variables in the final model." (PMID 40462804, 2025). "To further quantify the extent of lung injury, we measured BAL albumin and found that hemopexin-deficient animals had normal lung barrier integrity at baseline but increased permeability during the infection." (PMID 40232861, 2025). "In ACS, validated infection risk scores rely on clinical variables (age, Killip class, albumin, WBC count, vascular access, and device exposure) rather than hs-cTn." (PMID 41008500, 2025). "Serum albumin level, presence of hematuria, and rural residence were significantly associated with infection." (PMID 38987746, 2024). "Preoperative low albumin levels were significantly associated with postoperative incision infection, with a combined OR of 0.12 and a 95% CI of [0.02; 0.76], despite high study heterogeneity (I2 = 93%)." (PMID 39193402, 2024). "Many studies have confirmed that serum albumin level is an independent and predictive risk factor for surgical site infection in spinal surgery." (PMID 39671379, 2024). "According to reports, albumin (ALB) is associated with inflammation and is a powerful indicator of infection prognosis." (PMID 39741938, 2024). "Laboratory markers such as serum albumin and fasting blood glucose were independent risk factors for surgical site infection." (PMID 38558019, 2024). "The most prominent finding from this study is that low serum albumin increases the risk of surgical site infections." (PMID 38817798, 2024). "The research results showed that infection, psychiatric symptoms, serum sodium, albumin, NLR, and ELR were independent risk factors for AC, and these findings were consistent with the results of existing studies on poor prognosis factors in GIAI patients." (PMID 39741879, 2024). "Low serum albumin was also associated with an increased risk of deep and organ space-site infections." (PMID 38817798, 2024). "Low albumin levels increase the risk of infection, while high neutrophil counts indicate the presence of infection." (PMID 38561807, 2024). "Albumin can effectively evaluate the nutritional status and death risk of dialysis patients, and patients with low albumin have a higher risk of infection." (PMID 38589798, 2024). "First, a patient's poor clinical condition, including low albumin levels, transfusion dependency, and high risk of infection, increases the likelihood of surgical complications." (PMID 39017991, 2024). "The albumin, prealbumin, Intensive Care Infection Score (ICIS), Nutritional Risk Index, and white blood cell counts were found to be potential predictors." (PMID 39074134, 2024). "It was supported by research done in China, which showed decreased serum albumin was an independent risk factor for infection." (PMID 38987746, 2024). "We report lower albumin levels leading up to reinfection and a statistically significant association of severity between initial infection and reinfection (chi-squared value: 25,697, p-value: <0.0001) with a medium effect size (Cramer’s V: 0.20, DoF = 3)." (PMID 38992084, 2024). "Elevated GAR indicates increased serum glucose and decreased serum albumin, reflecting factors implicated in infection risks like poor nutrition, inflammation, and hypermetabolism." (PMID 39496632, 2024). "The existing literature shows that ALB has been used as a prognostic factor of infection, and it was correlated with a risk of death in patients with SFTS in a meta-analysis." (PMID 38806039, 2024).
infection (continued). "Multivariate logistic regression analysis of the identified important risk factors showed that infection, psychiatric symptoms, serum sodium, albumin, NLR and ELR were independent risk factors for AC." (PMID 39741879, 2024). "MELD score >18, raised TB > 6mg/dl, decreased sodium, low albumin level and infections are significantly associated with PSE recurrence." (PMID 38196479, 2024). "It is known that low serum albumin levels are an indicator of the severity of inflammation and susceptibility to infection complications." (PMID 37344786, 2023). "Serum albumin is a reliable marker of nutritional status, and a previous study showed an association between low serum albumin levels and infection." (PMID 36888568, 2023). "The results of multivariant regression analysis showed that for each increase of 1 g/L in serum albumin, the risk of serious infection would decrease by 43.2% (OR = 0.568, 95% CI 0.334–0.969, p = 0.038)." (PMID 38186651, 2023). "For each increase of 1 g/L in serum albumin, the risk of serious infection would decrease by 43.2% (OR = 0.568, 95% CI 0.334–0.969, p = 0.038)." (PMID 38186651, 2023). "Using a large cohort of patients evaluated in the ED for an infectious state, it was found that serum albumin levels used together with the SOFA score improved the prediction of 30-day mortality risk for patients with infections in the ED by 24.3%." (PMID 38137746, 2023). "Studies have shown that low serum albumin level delays wound healing, increases the risk of infection and reduces survival in patients with malignancy." (PMID 37851510, 2023). "Higher albumin level, and breakthrough infection were associated with discharge home following hospitalization." (PMID 37053224, 2023). "The immunological response is the main cause of the decrease in albumin levels that are linked to udder infection." (PMID 36899749, 2023). "Decreased albumin concentrations inhibit the activation of macrophages, impair the immune response, and increase susceptibility to infection." (PMID 37270566, 2023). "The observation that glycated albumin was associated with the likelihood of infection and the severity of COVID-19 syndrome is in agreement with both the role of glucose in masking the S spike epitopes and in modulating spike–ACE2 interactions." (PMID 36235696, 2022). "Logistic multivariate analysis showed that the length of hospital stay, antibiotic use, open injury, and serum albumin were all independent risk factors for MDROS infection in orthopedic trauma patients." (PMID 35126909, 2022). "Patients with low albumin levels are at a higher risk of developing severe infection and recurrent CDI." (PMID 35890064, 2022). "Eleven parameters showed a significant association with an infection including C-reactive protein, albumin, creatinine, and alcoholic etiology, which were independent variables in a predictive model." (PMID 36057565, 2022). "Serum albumin and globulin have been demonstrated to be implicated in diverse infection and inflammation." (PMID 34991649, 2022). "Physicians use classification tools to identify patients most at risk of developing a severe infection using white blood cell counts, serum albumin level, or serum creatinine level." (PMID 35856563, 2022). "Cardiothoracic ratio has been found to be positively associated with C-reactive protein and inversely associated with albumin, and can predict 2-year all-cause mortality and infection-caused mortality in HD populations." (PMID 35055386, 2022). "Logistic multivariate analysis showed that the length of hospital stay, antibiotic use time, open injury, and serum albumin level were independent risk factors of MDROS infection in orthopedic trauma patients." (PMID 35126909, 2022). "Results showed that patients with BK virus active infection were associated with a deceased donor, had lower direct bilirubin levels, a higher proportion of albumin in serum protein electrophoresis, and lower red blood cells and neutrophil counts." (PMID 35223891, 2022).
infection (continued). "From a clinical perspective, Albumin concentration is a factor determining the length of hospitalization, infection susceptibility, and in-patient death." (PMID 35893870, 2022). "Caburet reported Nutrition Risk Index (NRI, NRI = 1.519 × serum albumin (g/L) + 41.7 × (present weight/usual weight)) to be an independent risk factor for postoperative infection-related and healing-related complications in HNC patients receiving surgery." (PMID 36558490, 2022). "The results of binary logistic regression analysis showed that a shorter time from injury to surgery, longer operation time, and lower preoperative albumin were risk factors for postoperative incision infection." (PMID 36514037, 2022). "Surprisingly, low albumin had a more significant impact on infection risk with an OR of 200 when comparing low versus high albumin." (PMID 35119125, 2022). "Albumin is the main protein in human serum, and hypoalbuminemia, a historic index of malnutrition, has recently been associated with infection in orthopedics." (PMID 36309703, 2022). "Remarkably, low serum albumin was found to be significantly associated with infection (OR = 479.963, 95% CI 61.59 ‐ 3740.33, p < 0.0001) and this finding was surprisingly higher than BMI or HbA1c‐associations." (PMID 35119125, 2022). "Previous studies showed that an albumin level lower than 3.0 to 3.5 g/dL was associated with increased mortality and the risk of infection in critically ill patients as well as perioperative patients." (PMID 36233660, 2022). "The time from injury to operation < 10.5 days, preoperative albumin value < 38.5 g/L, and operation time > 84.5 minutes were determined to be risk factors for postoperative incision infection (p < 0.05)." (PMID 36514037, 2022). "For patients predicted to be at high risk of infection, clinicians can apply more stringent glycemic control, close monitoring of albumin levels, and more rigorous wound care." (PMID 36050996, 2022). "Only during infection in the presence of albumin, epithelial cells induced genes associated with ER-stress and UPR." (PMID 34710198, 2021). "Tamoxifen, an estrogen receptor modulator; microcrystals, such as MSU; an excess of glucose; autoantibodies against extracellular DNA and ribonucleoproteins; and redox imbalance caused by albumin oxidation are triggers of infection-independent NET release." (PMID 33933883, 2021). "Systemic inflammation in severe infection alters the function and kinetics of albumin, which in turn can increase the risk of worse clinical outcome." (PMID 33925831, 2021). "Of note, infection with the C. glabrata hap5Δ mutant caused lower levels of AUS1 gene expression as compared to infections with the WT in the presence of albumin, supporting that iron is required for this process." (PMID 34710198, 2021). "Previous studies have shown that lower serum albumin was associated with infection and increased mortality in the critically ill subjects." (PMID 33397522, 2021). "In patients with intra-abdominal infections, host-related factors dominate over the type, extent, and source of infection in determining prognosis, and low serum albumin is one of few identified risk factors for mortality." (PMID 33925831, 2021). "Host-associated opportunistic pathogens encounter albumin during commensalism and when causing infections." (PMID 34154403, 2021). "As serum albumin is also an indicator of inflammatory conditions, it is necessary to control associated variables such as inflammation and infection in future studies." (PMID 33377565, 2021). "Albumin and globulin, the two main fractions of the serum protein, have proven to be critical markers linked to inflammation and infection." (PMID 34206598, 2021). "Expression of gene LL37, encoding for an antimicrobial peptide, was up-regulated by albumin both during infection and in uninfected conditions." (PMID 34710198, 2021).
infection (continued). "Correlation of albumin levels and severity of the infection is presented through the specific CRP/albumin ratio, already marked as an independent risk factor for severe COVID-19 infection." (PMID 33968298, 2021). "An albumin level <3.5 g/dL was associated with ~2.5-fold increased risk of surgical site infections in orthopedics." (PMID 33925831, 2021). "Increased ALP levels were associated with lower serum albumin levels and increased risk of infection-related mortality, contributing to adverse clinical outcomes in ICH patients." (PMID 34526953, 2021). "Inclusion of preoperative serum albumin levels enabled development of a validated stratification scoring system to predict accurately the risk of surgical site infection after esophagectomy in patients with esophagus carcinoma." (PMID 33925831, 2021). "Multivariate Cox proportional hazards model disclosed that higher age (HR 19.29, 95% CI 3.76–99.03, P < 0.001) and lower serum albumin (HR 0.01, 95% CI 0.00–0.17, P = 0.001) predicted infection-associated mortality." (PMID 31964940, 2020). "Spline curve analysis revealed that higher albumin-corrected serum calcium level was associated with incremental increase in risk of infection-related death." (PMID 32286455, 2020). "Whereas the independent predictors for infection-associated mortality included higher nHF (HR 1.033) as well as higher age (HR 19.29) and lower serum albumin (HR 0.01, P = 0.001)." (PMID 31964940, 2020). "Our final clinical model for adjustment of qPCR variables included the presence of a central line, cephalosporin antibiotics, and albumin as associated with subsequent infection." (PMID 32699120, 2020). "Aggressive interventions to maintain adequate hemoglobin and albumin and prompt identification and treatment of infection perioperatively are encouraged to reduce the risk of anastomotic leak." (PMID 32024132, 2020). "A previous study reported an association between low serum albumin, infection and increased morbidity or mortality outcome among critically ill patients." (PMID 33312698, 2020). "The correlation with markers of infection and inflammation has been confirmed by others, with lower plasma glutamine levels found to be associated with lower albumin levels, higher CRP levels, and higher circulating IL-1β and IL-6 levels." (PMID 32028696, 2020). "In our study, we observed that serum transferrin level was positively correlated with serum albumin and hemoglobin, which suggested that patients with lower transferrin had poor nutritional status and, in turn, they were more susceptible to infection." (PMID 32922172, 2020). "The association of albumin-corrected serum calcium level with infection-related death was significantly enhanced in younger patients and in patients with lower serum albumin level." (PMID 32286455, 2020). "As reported, a lower level of albumin was significantly associated with infection and mortality among these patients." (PMID 32406300, 2020). "The results of a univariate analysis demonstrated that the changes in lymphocytes, albumin, and the use of antibiotics were infection risk factors in the ICU patients." (PMID 32993493, 2020). "Although the synthesis of albumin and pre-albumin is influenced by dietary protein intakes, non-nutritional factors such as inflammation, overhydration, physiological stress, and infection are also implicated in low levels of serum albumin or pre-albumin." (PMID 32933198, 2020). "Spline curve analysis also showed that albumin-corrected serum calcium level was incrementally and significantly associated with increased risk of infection-related death, especially when the albumin-corrected serum calcium level exceeded 10 mg/dL." (PMID 32286455, 2020). "In this study, delta albumin was associated with adverse postoperative surgical site infection, delayed wound healing and death within 30 days." (PMID 32664910, 2020).